STAT3 (signal transducer and activator of transcription 3)
Diseases named in the same sentence as STAT3 in open-access papers (continued):
Sharing a sentence is not in itself a finding about the gene and the disease.
tumor (continued). "We confirm it modulates differentiation and expression of important tumor-promoting signaling pathways in macrophages, such as NFκB, STAT3, Notch 3 and IRAK1." (PMID 25599228, 2015). "In summary, we found that cisplatin-selected resistance (oncogenic resistance) transactivates STAT3/Snail pathway, and the axis regulates tumor migration/invasion, cancer stem-like cell properties, and cisplatin resistance in ATRT cells." (PMID 25638155, 2015). "STAT3 is involved in various aspects of tumor microenvironment to cultivate a favorable environment for cancer development." (PMID 26631279, 2015). "It is likely that both STAT3 inactivation and ROS contributed to the inhibition of STAT3 signaling and the induction of apoptosis of tumor cells." (PMID 26010889, 2015). "Our work provides evidence of an oncogenic role of ERp57 in regulating STAT3 activation in tumor development and resistance." (PMID 25605256, 2015). "After neutralizing IL-6 with a blocking mAb, IL-17 stimulation still significantly increased p-STAT3 expression in tumor cells even though STAT3 activation was diminished." (PMID 26524953, 2015). "The percentage of STAT3- and Snail-positive cells were dramatically increased in the four of five tumor-relapse samples (patients 1, 2, 4, and 8) compared with the tumor samples from the first surgery." (PMID 25638155, 2015). "With improvements in cyclization, STAT3-targeting ODN seems more amenable to systemic administration and can yield optimum effects by downregulating STAT3 target genes and by suppressing tumor growth." (PMID 26631279, 2015). "Blocking of the STAT3 signaling abrogated IL-6-induced Jagged-1 expression, effectively inhibited the growth of the trastuzumab resistant cells, and enhanced the anti-tumor activities of trastuzumab in the resistant cells." (PMID 25669984, 2015). "To further confirm the reduction of tumor was correlated with cancer stem cells, we used immunohistochemical staining to detect the p-STAT3 as well as CSCs markers OCT4, SOX2 and ALDH1." (PMID 26556875, 2015). "WP1066 has been shown to effectively block JAK2 and Stat3 activation in multiple tumor cell types, including glioma cell lines." (PMID 25881542, 2015). "For example, wogonin suppresses tumor cell migration by inactivating the STAT3 signaling pathway in human alveolar cell adenocarcinomas." (PMID 25638155, 2015). "Among the Stat proteins, persistent activation of Stat3 is detected in human cancer cell lines and tumor tissues." (PMID 26169986, 2015). "Deletion of STAT3 in KrasG12D/+ lung tumours and human AC resulted in an increased tumour growth, higher tumour grade, increased vascularization, changes in the tumour microenvironment and significantly reduced survival." (PMID 25734337, 2015). "Surprisingly a gradually higher CB1 expression was found from peripheral to central tissue of the dissected tumor from one representative patient and these levels inversely correlate with STAT3 activity status." (PMID 26008966, 2015). "This concept is further supported by recent publications demonstrating that ADT and enzalutamide reduced cancer load and promoted PC metastasis by affecting tumor and stroma in a process involving STAT3." (PMID 26593949, 2015). "In line, those tumours with advanced stage (grade III) had significantly less STAT3 expression, indicating that STAT3 downregulation seems to be beneficial for tumour progression." (PMID 25734337, 2015). "The combination treatment of TG101348 and erlotinib obviously decreased the expressions of EGFR, p-EGFR, Bcl-xL and survivin, suppressed the activation of STAT3, induced apoptosis and inhibited tumor growth of EGFR-mutant NSCLC cells in vivo." (PMID 25869210, 2015).
tumor (continued). "Among them, an important feature of STAT3 is its crucial role in stromal cells, including immune cells, which are recruited to tumor microenvironments to promote cancer progression." (PMID 26501341, 2015). "Although it's rather clear that STAT3 signaling play a crucial role in tumor initiation, viability, angiogenesis and metastasis, the function of STAT3 signaling in HNSCC CSCs is still an open question." (PMID 26556875, 2015). "Increasing evidence displayed that constitutive activation of STAT3 gave rise to neoplasm invasion and metastasis." (PMID 26078947, 2015). "Treatment of keratinocytes with the TPA tumor promoter results in increased mitochondrial S-P STAT3 via a PKCε-dependent mechanism." (PMID 26106584, 2015). "In conclusion, our results suggest that IL-17-mediated tumor angiogenesis involves activation of the STAT3/GIV signaling pathway and subsequent up-regulation of VEGF production in NSCLC cells." (PMID 26524953, 2015). "Taken together, we conclude that STAT3 and Snail are both essential for promoting tumor-initiating capabilities in ATRT cancer cells and play a key role in chemoresistance-induced cancer stem-like properties of ATRT." (PMID 25638155, 2015). "Other factors, such as STAT3, cooperate with the immune system to active immune related functions in the host to reduce tumor progression." (PMID 26497558, 2015). "Consistence with these findings, we found that the level of phosphorylation of Stat3 at Y705 was higher in tumor tissues compared with the paired neighboring tissues." (PMID 26376676, 2015). "Mechanistic investigations reveal that a miR-197-mediated CKS1B/STAT3 axis exerts tumor progression regulated by various oncogenic genes (Bcl-2, c-Myc, and cyclin D1), and PD-L1 is a putative biomarker of this axis." (PMID 25597412, 2015). "On the other hand, IL-17 promotes the carcinogenesis primarily by arousing the activation of Stat3 signaling pathway to induce resistance to apoptosis and promote angiogenesis by which facilitate tumor growth and progression." (PMID 25706309, 2015). "We conclude that IL-1 signaling antagonizes IL-11/STAT3 mediated pathology and the genetic deletion of IL-1RT1 results in increased tumor burden." (PMID 25528766, 2015). "Taken together, these results indicate that STAT3 upregulates Snail and contributes to tumor invasion and motility in ATRT cells." (PMID 25638155, 2015). "The regulation of EMT involves complex signaling pathways mainly including TGF-β, Wnt/β-catenin, Stat3, Notch, and Hedgehog pathway, leading to enhanced tumor invasion and metastasis." (PMID 25879771, 2015). "They found that fatty acid-binding protein 7 was one of the most commonly overexpressed genes in ccRCC and was able to promote tumor growth through the activation of STAT3 and ERK signaling pathways." (PMID 28031890, 2015). "S100A9-mediated release of IL-6 requires the crosstalk of tumor cells with monocytes through the activation of NF-κB and STAT-3." (PMID 26315114, 2015). "The JAK/STAT3 signal plays an important role in tumor cell proliferation, survival, and invasion and participates in the development of inflammation and neuropathic pain." (PMID 26649065, 2015). "EB selectively inhibited constitutive as well as IL-6-induced phosphorylation of STAT3 and induced apoptosis of STAT3-dependent tumor cells." (PMID 26010889, 2015). "In the present study, we unraveled a novel mechanism of Fas-mediating tumor cell motility, which depended on the upregulation of Fascin via activation of STAT3." (PMID 25992623, 2015). "Leptin is reported to be anti-apoptotic in tumor cells, consistent with an upregulation of NFκB and STAT3 anti-apoptotic transcription factors." (PMID 25599228, 2015). "Conclusively, this study is the first research to examine Lycorine's anti-cancer mechanistic role of JAK/STAT3 signaling in PCa tumor growth and metastasis and identify a perturbance in a plethora of JAK/STAT signaling proteins in PCa." (PMID 25915156, 2015).
tumor (continued). "Signal transducer and activator of transcription 3 (Stat3) is a critical signaling pathway that is involved in the formation of tumor microenvironment through regulating downstream proinflammatory cytokines and factors promoting tumor growth and progression." (PMID 25706309, 2015). "Since high SOCS1 levels have been described to suppress pY-STAT3, we looked at the activity of STAT3 in these tumours." (PMID 25820993, 2015). "STAT3 activation leads to the inhibition of apoptosis and tumor progression in TNBC, and its dysfunction induces cell death in vitro and in vivo, implicating STAT3 as an attractive therapeutic target." (PMID 26528725, 2015). "The balance between STAT1 and STAT3 activation within a tumour is paramount for the resulting effects on the tumour cell itself and the microenviroment." (PMID 25880691, 2015). "Pre-treating human PCSCs (CD133/AC133+α2β1hi) with increasing concentrations of STAT3 inhibitor LLL12 abrogated their tumor-propagating ability in vivo." (PMID 25595909, 2015). "Most of these tumor-derived factors activate signaling pathways which involve STAT3 or Janus kinase (JAK) in myeloid precursor cells." (PMID 26078490, 2015). "The present study has proven that there is a close relationship between STAT3 and cell adhesion molecules, extracellular matrix degrading enzymes, tumor angiogenesis, metastasis through MMP, VEGF, and other related gene interactions." (PMID 26788112, 2015). "Western blot analysis was performed to assess Akt, phosphorylated (p)-Akt, signal transducer and activator of transcription (STAT) 3, p-STAT3 and p-p65 in tumor cells following treatment with thioridazine." (PMID 26095429, 2015). "Cancer cells induce NFkB signalling in tumour-associated macrophages (TAMs), triggering their IL6 secretion, which in turn stimulates the neoplastic proliferation via STAT3 activation." (PMID 25915429, 2015). "Abnormal p-STAT3 aggregation can also be observed in the proliferation of vascular endothelial cells which means that p-STAT3 is involved in tumor angiogenesis." (PMID 26788112, 2015). "In this study, using the Stat3 specific inhibitor S3I-201 or Stat3's siRNA method, we found Stat3 function is critical in tumor initiation of HCC." (PMID 26376676, 2015). "Similar to EB, Stattic also inhibited the growth of A549 and MDA-MB-468 cells more than that of the MDA-MB-453 cells, further indicating that the inhibition of EB on tumor cell growth correlated with the EB-dependent inactivation of STAT3." (PMID 26010889, 2015). "STAT3 is regarded as the main effector of IL-6 signaling and plays an important role in the survival and proliferation of tumor cells and immune cells." (PMID 26516076, 2015). "It has also been documented that Fascin can increase the motility of tumor cells and is a direct target gene of STAT3." (PMID 25992623, 2015). "Constitutive STAT3 activation within the tumour cell is transmitted to the tumour microenvironment where it induces tumour-associated inflammation." (PMID 25880691, 2015). "The present study has proven that there is a close relationship between STAT3 and cell adhesion molecules, extracellular matrix degrading enzymes, angiogenesis, metastasis, and promotion tumor angiogenesis through MMP." (PMID 26788112, 2015). "PG-S3–002- treated cells reduced tumor formation by approximately 60% as compared to control tumors, which is similar to tumors formed by STAT3 KD." (PMID 26314961, 2015). "Activated STAT, particularly STAT3, inhibits tumor cell apoptosis, accelerates the cell cycle and thus leads to tumorigenesis." (PMID 25574225, 2015). "Several anti-apoptotic proteins, such as Survivin and members of the Bcl family (Bcl-xl, Bcl-2 and Mcl-1) which are known to be crucial for tumor cell survival, are direct target genes of STAT3 and are down-regulated as a consequence of STAT3 inhibition." (PMID 26474284, 2015).
tumor (continued). "Restoring the genetic function of the SOCS3 gene by demethylation or SOCS3 gene transfection was shown to suppress tumor cell growth by attenuating activation of signal transducer and activator of transcription 3 (STAT3) in several human cancer cell lines." (PMID 25695729, 2015). "Disrupting the aberrant activation of STAT3 or NF-κB signaling is able to dramatically suppress tumor progression." (PMID 26417930, 2015). "It has reported that TQ represses tumor growth by modulating p38, STAT-3, PPAR-γ and other signaling pathways." (PMID 26416455, 2015). "Our results indicate that WP1066 can inhibit tumor angiogenesis and brain metastasis mediated by Stat3 in endothelial and tumor cells." (PMID 25881542, 2015). "We have determined that PTK6 promotes tumor initiation and progression and is important for regulation of STAT3, FAK, and BCAR1." (PMID 26247733, 2015). "Collectively, these data suggest that anti-tumor activity and pro-apoptotic effect of icaritin on human U266 cells is associated with the mechanism involved in targeting IL-6/JAK2/STAT3 signaling pathway." (PMID 25865044, 2015). "The signal transducer and activator of transcription 3 (Stat3) regulates the expression of numerous critical mediators of tumor formation and metastasis, and it plays a role in the tumorigenesis and progression of virtually all malignancies including NPC." (PMID 26314966, 2015). "The results showed that STAT3 phosphorylation was significantly activated in tumor tissues compared with normal urothelial cells." (PMID 26245871, 2015). "The tumour promoting effects of STAT3 affect both innate and adaptive immune responses and have made it an attractive target for cancer therapy." (PMID 25880691, 2015). "In PC3 cells injected in vivo, STAT3 knockdown markedly decreases tumorigenic potential and induces intense tumor apoptosis." (PMID 25785244, 2015). "We used EMSA to detect constitutive NF-κB/STAT3 activity in BL- and MM-like neoplasms that spontaneously developed in single-transgenic IL6 (interleukin-6) or MYC (c-Myc) mice, or in double-transgenic IL6MYC mice." (PMID 25838973, 2015). "This Stat3-orchestrated interaction between endothelial and tumor cells resulted in a number of cellular activities involved in angiogenesis, including endothelial cell migration, invasion and tube formation." (PMID 25881542, 2015). "The collaborative functions of STAT3 and NF-κB make a link from inflammation to cancer and the mechanism inflammatory responses have a decisive role at different stages of tumor development becomes gradually clear." (PMID 26631279, 2015). "We first investigated the involvement of STAT3 and Snail in cancer stem-like properties and tumor-initiating capability of ATRT-CisR cells using sphere-forming and self-renewal assays." (PMID 25638155, 2015). "RFP imaging revealed that tumor volumes in mice transplanted with ATRT-CisR/sh-STAT3 cells were significantly decreased with cisplatin (1 μg/ml) compared to ATRT-CisR/sh-Scr cells with cisplatin (1 μg/ml)." (PMID 25638155, 2015). "The persistent activation of Stat3 or Stat5 is found in many human tumor cells and contributes to their growth and survival." (PMID 25809097, 2015). "For instance, IL-6 secreted by tumor-infiltrating macrophages can increase the tumor-initiating capacity and drug resistance capability of neoplastic stem-like cell populations by inducing Stat3 and Hedgehog signaling." (PMID 27158195, 2015). "In keeping with this, knockdown of STAT3 inhibited cell migration and blocked tumour spheroid formation in a range of different MPNST cell lines tested." (PMID 26697523, 2015). "Accumulating studies support that inhibition of SOCS3 expression promoted STAT3 activation, enhanced hepatic fibrosis, increased proliferation and tumor aggressiveness." (PMID 26416445, 2015). "The anti-tumour action of LDFI was associated with the inhibition of several leptin-induced pathways such as JAK2, STAT3, AKT and MAPK and a reduction in Cyclin D1 expression." (PMID 25721149, 2015).
tumor (continued). "Previous studies have confirmed that STAT3 alterations affect Bcl-2 and Bax protein expression and induce inflammation and apoptosis in many types of tumor cells." (PMID 25946003, 2015). "These infiltrating tumor cells showed activation of EGFRvIII/STAT3 signaling and expression of stemness markers (Nestin and Sox2) in vivo." (PMID 25992628, 2015). "Blockade of STAT3 pathway synergistically increased anti-tumor activity of gefitinib, as well as another EGFR inhibitor (erlotinib) (data not shown)." (PMID 25928246, 2015). "Targeting STAT3 present a feasible stategy to weaken the supporting function of tumor microenvironment and improving the therapeutic effect for cancer." (PMID 26631279, 2015). "In conclusion, the current meta-analysis suggests that p-STAT3 expression in the tumor sample of digestive system was a promising predictor of both OS and DFS." (PMID 26024373, 2015). "More importantly, our study indicates that Stat3 activation orchestrates the interaction between endothelial cells and tumor cells, which is known to be crucial for tumor growth and metastasis." (PMID 25881542, 2015). "The activated STAT3 stimulates tumor stromal immune cells, whose recruitment promotes tumor progression." (PMID 26164207, 2015). "And level of p-STAT3 expression is closely related with lymph node metastasis and tumor cell differentiation." (PMID 26024373, 2015). "Inhibiting STAT3 activation with a small molecule inhibitor of JAK, an upstream kinase that phosphorylates and activates STAT3, synergistically increased the anti-tumor activity of gefitinib in vitro." (PMID 25928246, 2015). "There is high expression of STAT3 in many kinds of tumor cells, so the research of STAT3 in tumors has become a hot topic." (PMID 26788112, 2015). "There is accumulating evidences of a role of PI3K/AKT and JAK/STAT3 signaling pathways in tumor metastasis and EMT." (PMID 26515594, 2015). "Constitutive expression of STAT3 induces a decrease in Necdin expression at the mRNA and protein levels in tumor cell lines." (PMID 25012566, 2014). "Lastly, when T98G cells were injected into nude mice, G6 treatment significantly reduced tumor volume and this was concomitant with significantly decreased levels of phospho-Jak2 and phospho-STAT3 within the tumors themselves." (PMID 25162558, 2014). "Ectopic expression of constitutive STAT3 is sufficient to induce transformation of rodent cells in vitro and tumor formation in vivo." (PMID 24662938, 2014). "In the present study, we revealed that those compounds inhibit tumor proliferation and differentiation of macrophages toward M2 phenotype via inhibiting STAT3 activation, whereas inhibitory mechanism of those compounds on MDSCs function has not been unclear." (PMID 24738052, 2014). "Another possibility is that the discrepancies among published studies are related to cell-type specificity, such that STAT3 is oncogenic in one type of cancer whereas it is a tumor suppressor in another." (PMID 24995504, 2014). "Various types of tumor cells exhibited constitutively phosphorylated STAT3 within the nucleus, which has been shown to promote uncontrolled malignant tumor growth and relate with a poor prognosis of patients." (PMID 24624997, 2014). "Among several changes seen in the tumor microenvironment following Embelin administration, the levels of IL-6/STAT3 were significantly decreased and resulted in a reduced population of Th17 cells." (PMID 24987392, 2014). "Natural compounds, such as CA and OA, exert inhibitory effects on STAT3 activation in macrophages, MDSCs, and tumor cells." (PMID 24738052, 2014). "Recently, STAT3 was found to have an important role in maintaining cancer stem cells in vitro and in mouse tumor models, suggesting STAT3 is integrally involved in tumor initiation, progression and maintenance." (PMID 24743778, 2014). "STAT3 also mediates regulatory T cell (Treg) expansion in tumors and is necessary for the development of Th17 cells, which can promote tumor growth." (PMID 25149535, 2014).